SIRT4 (sirtuin 4)
Description:
Acts as a NAD-dependent protein lipoamidase, biotinylase, deacetylase and ADP-ribosyl transferase. Catalyzes more efficiently removal of lipoyl- and biotinyl-than acetyl-lysine modifications. Inhibits the pyruvate dehydrogenase complex (PDH) activity via the enzymatic hydrolysis of the lipoamide cofactor from the E2 component, DLAT, in a phosphorylation-independent manner. Catalyzes the transfer of ADP-ribosyl groups onto target proteins, including mitochondrial GLUD1, inhibiting GLUD1 enzyme activity. Acts as a negative regulator of mitochondrial glutamine metabolism by mediating mono ADP-ribosylation of GLUD1: expressed in response to DNA damage and negatively regulates anaplerosis by inhibiting GLUD1, leading to block metabolism of glutamine into tricarboxylic acid cycle and promoting cell cycle arrest. In response to mTORC1 signal, SIRT4 expression is repressed, promoting anaplerosis and cell proliferation. Acts as a tumor suppressor. Also acts as a NAD-dependent protein deacetylase: mediates deacetylation of 'Lys-471' of MLYCD, inhibiting its activity, thereby acting as a regulator of lipid homeostasis (By similarity). Does not seem to deacetylate PC. Controls fatty acid oxidation by inhibiting PPARA transcriptional activation. Impairs SIRT1-PPARA interaction probably through the regulation of NAD(+) levels. Down-regulates insulin secretion.
Synonyms: SIR2L4
Tractability: Small molecule: a high-quality ligand is known. PROTAC: ubiquitination databases record sites on it.
Target class: Histone deacetylase; HDAC class III; Epigenetic regulator; Eraser
Gene: Protein-coding gene on chromosome 12 (120,292,162 to 120,313,249, forward strand). Ensembl gene ENSG00000089163.
Subcellular location: Mitochondrion matrix
Pathways (Reactome):
Metabolism: Regulation of pyruvate dehydrogenase (PDH) complex
Organelle biogenesis and maintenance: Transcriptional activation of mitochondrial biogenesis
Gene Ontology:
Molecular function: NAD+ poly-ADP-ribosyltransferase activity; NAD+-protein-cysteine ADP-ribosyltransferase activity; NAD-dependent protein biotinidase activity; NAD-dependent protein lipoamidase activity; NAD-dependent protein lysine deacetylase activity; protein binding; histone deacetylase activity; NAD+-protein mono-ADP-ribosyltransferase activity; acyltransferase activity, transferring groups other than amino-acyl groups; lipoamidase activity; NAD binding; NAD+ binding; zinc ion binding
Biological process: negative regulation of fatty acid oxidation; negative regulation of insulin secretion; negative regulation of pyruvate decarboxylation to acetyl-CoA; DNA damage response; glutamine metabolic process; mitochondrion organization; peptidyl-lysine deacetylation; positive regulation of lipid biosynthetic process; tricarboxylic acid metabolic process; cellular response to hypoxia; chromatin remodeling; negative regulation of cardiac muscle cell apoptotic process; negative regulation of establishment of protein localization to mitochondrion
Cellular component: mitochondrial matrix; mitochondrion; mitochondrial inner membrane
Genetic constraint (gnomAD): Loss-of-function variants: 23 observed, 27.79 expected, observed/expected ratio (o/e) 0.83, 90% interval 0.6 to 1.17. The upper end of that interval is the gene's LOEUF score, 1.17, which puts it in group 5 of 6, group 1 being the genes least tolerant of losing a copy. Missense variants: 361 observed, 424.69 expected, observed/expected ratio (o/e) 0.85, 90% interval 0.78 to 0.93. Synonymous variants: 155 observed, 168.08 expected, observed/expected ratio (o/e) 0.92, 90% interval 0.81 to 1.05.
Homologues: Orthologues: chimpanzee SIRT4 (99% identical), macaque SIRT4 (97% identical), pig SIRT4 (89% identical), rabbit SIRT4 (88% identical), mouse Sirt4 (86% identical), rat Sirt4 (84% identical), dog SIRT4 (84% identical), guinea pig SIRT4 (84% identical), tropical clawed frog sirt4 (61% identical), zebrafish sirt4 (60% identical), Drosophila melanogaster Sirt4 (46% identical), Caenorhabditis elegans sir-2.2 (44% identical), and 1 more. Paralogues in human: SIRT5 (27% identical), SIRT6 (25% identical), SIRT7 (25% identical), SIRT3 (24% identical), SIRT1 (23% identical), SIRT2 (22% identical).
Diseases named in the same sentence as SIRT4 in open-access papers:
SIRT4 is named in the same sentence as 118 diseases in open-access papers, as found by Europe PMC text mining. Sharing a sentence is not in itself a finding about the gene and the disease. The quoted sentences say what the papers report.
breast cancer (25 papers, 2013 to 2025). A primary or metastatic malignant neoplasm involving the breast. "Examples within breast cancer include DNMT-1 gene disinhibition and SIRT4 loss, mediated by hypermethylation, which promotes breast cancer self-renewal." (PMID 36900364, 2023). "SIRT4 is downregulated in breast cancer using the TCGA breast cancer database analysis, and SIRT4‐deficient mice are more likely to exhibit tumor formation and lung metastasis." (PMID 40625712, 2023). "SIRT4 regulates the catabolism of multiple nutrients, and the loss of SIRT4 promotes the self-renewal of breast cancer stem cells." (PMID 36010594, 2022). "In breast cancer, the loss of SIRT4 promotes the breast cancer stem cell's self-renewal and is found related to the poor prognosis of patients with invasive breast cancer." (PMID 35154350, 2022). "H4K16ac and breast cancer susceptibility gene 1 (BRCA1) are new major targets for SIRT4 in breast cancer." (PMID 33585187, 2020). "Loss of SIRT4 expression is strongly associated with short-term metastasis in breast cancer patients." (PMID 33585187, 2020). "To prove the involvement of SIRT1 in SIRT4-deficiency-induced malignancy, we established stable breast cancer cell lines (MDA-MB-468 and MCF-7) expressing two independent shRNAs that target SIRT1 and SIRT4." (PMID 32863939, 2020). "In terms of breast cancer, low SIRT4 expression was linked with poor overall survival in breast cancer patients, especially in Luminal A patients." (PMID 32863939, 2020). "Moreover, the loss of SIRT4 expression showed a strong association with short-term metastasis in breast-cancer patients." (PMID 33585187, 2020). "Indeed, a variety of human cancers including lung, bladder, gastric, and breast cancers as well as leukemia have decreased SIRT4 expression and lower SIRT4 level was associated with poorer prognosis." (PMID 33117704, 2020). "Intriguingly, although more tumor tissue samples were found SIRT4 positive than adjacent nontumor tissue samples by immunohistochemical staining, low SIRT4 expression was associated with poor overall survival in breast cancers patients, especially in Luminal A patients." (PMID 32863939, 2020). "In small cell lung cancer, leukemia, gastrointestinal tumors and breast cancer, the expression of SIRT4 is reduced 16-20." (PMID 38773972, 2024). "SIRT4 is aberrantly expressed in a variety of tumor diseases; studies in breast cancer have found that SIRT4 expression increases with time when breast cancer cells are cultured under low glycemic conditions." (PMID 40625712, 2023). "In contrast, SIRT4 enhanced tamoxifen sensitivity in breast cancer cells by inhibiting the STAT3 signaling pathway." (PMID 40625712, 2023). "Previous studies have also showed the downregulation of SIRT4 in gastric, thyroid and breast cancer." (PMID 36809279, 2023). "LncRNA MALAT1 attenuated cardiac hypertrophy via the miRNA-93-5p/SIRT4 axis, whereas circOMA1 aggravated breast cancer by regulating the miRNA-1276/SIRT4 axis." (PMID 37191431, 2023). "In a study on breast cancer, SIRT4 was found to enhance the sensitivity of breast cancer cells to tamoxifen." (PMID 40625712, 2023). "The authors suggested the crosstalk between the mitochondrial and nuclear sirtuins following SIRT1 downregulation by SIRT4 expression culminated in the suppression of breast cancer." (PMID 36291902, 2022). "While some studies report that SIRT4 expression is upregulated in breast cancer, others report downregulation." (PMID 36291902, 2022). "Supporting this, the downregulation of SIRT4 in breast cancer cell lines resulted in decreased expression of SIRT1 and stem cell markers Oct4, Sox2, and Nanog." (PMID 36291902, 2022). "Collectively, these data indicated that SIRT4 depletion affected glutaminolysis in mammary tumor cells." (PMID 32863939, 2020). "Gene Ontology (GO)-analysis revealed the enriched signatures related to endogenous SIRT4-dependent transcription in breast cancer, namely, stem cell signaling." (PMID 32863939, 2020).
breast cancer (continued). "In conclusion, we found that SIRT4 regulation of BITCs negatively modulated mammary tumorigenesis through suppression of SIRT1 via glutamine metabolism and that SIRT4 deficiency decreased H4K16ac and BRCA1 expression in breast cancer." (PMID 32863939, 2020). "Consistent with other studies 17, 24, our analysis performed based on data from the TCGA database validated that SIRT4 was downregulated in breast cancer." (PMID 32863939, 2020). "Xing and collaborators showed that SIRT4 increased the sensitivity of breast-cancer cells to tamoxifen." (PMID 33585187, 2020). "CtBP also down-regulated SIRT4 expression to promote the growth of breast-cancer cells and inhibited their apoptosis." (PMID 33585187, 2020). "Wang and colleagues found that down-regulation of SIRT4 expression promoted glutamine decomposition, promoted the growth of breast-cancer cells and inhibited their apoptosis." (PMID 33585187, 2020). "Inhibition of SIRT4 expression by CtBP helped to maintain the pH homeostasis of breast-cancer cells and was beneficial to their growth." (PMID 33585187, 2020). "Here, we show that SIRT4 possesses its tumor-suppressive effect on breast cancer by inhibiting glutamine metabolism and thereby affecting the protein levels of SIRT1, which modulates the acetylation patterns of histones H4 and regulates stemness via BRCA1." (PMID 32863939, 2020). "High-throughput real-time polymerase chain reaction analyses have shown that SIRT4 expression in breast-cancer tissue is predominantly lower than that in paracancerous tissue." (PMID 33585187, 2020). "SIRT4 inhibits the growth of cells and increases the sensitivity of ER positive breast cancer to tamoxifen." (PMID 33585187, 2020). "Western blotting showed that, compared with the negative control cells, STAT3 expression was weaker in the nucleus and stronger in the cytoplasm following SIRT4 overexpression in both breast cancer cell lines." (PMID 31573734, 2019). "The breast cancer cell line MCF7 was treated with 20 μmol/L tamoxifen or DMSO for 48 hours after overexpression or depletion of SIRT4." (PMID 31573734, 2019). "We also used SIRT4‐specific short interfering RNAs (siRNAs) to deplete SIRT4 levels in the two breast cancer cell lines, and observed that the IC50 increased after SIRT4 depletion." (PMID 31573734, 2019). "The levels of the MYC proto‐oncogene (MYC) and cyclin D1 (CCND1) were detected by western blotting and quantitative reverse transcription‐polymerase chain reaction in breast cancer cells with SIRT4 overexpression or depletion." (PMID 31573734, 2019). "Taken together, these results demonstrate that SIRT4 enhances the tamoxifen sensitivity of breast cancer cells by inhibiting the STAT3 signaling pathway." (PMID 31573734, 2019). "This study focused on the role of SIRT4 in the tamoxifen sensitivity of breast cancer and demonstrated that SIRT4 blocks the transcription and translation of MYC and CCND1 in ER‐positive breast cancer, through the STAT3 pathway." (PMID 31573734, 2019). "Sirt4 KO mice can be spontaneously infected with lung cancer, liver cancer, breast cancer, and lymphomas." (PMID 31817470, 2019). "This study demonstrates that SIRT4 enhances the sensitivity of breast cancer to tamoxifen via STAT3 pathway inhibition due to decreased STAT3 Y705 phosphorylation." (PMID 31573734, 2019). "Although some studies indicate an upregulation of SIRT4 expression, others report downregulation, which may be due to the variations in the breast cancer cell types or the methodologies used." (PMID 41304967, 2025). "This discrepancy precludes the possibility of targeting SIRT4 in the treatment of breast cancer." (PMID 41304967, 2025). "The pattern of SIRT4 expression in breast cancer is controversial." (PMID 41304967, 2025). "SIRT4 might affect breast cancer CSCs by altering SIRT1 expression, targeting H4K16Ac and BRCA1, and affecting the process of autophagy." (PMID 38397988, 2024).
breast cancer (continued). "Notably, SIRT4 plays a pivotal role in the suppression of tumorigenesis across a spectrum of cancer types (such as colorectal cancer, breast cancer, prostate cancer, etc.), consistent with its low expression levels in these tumors." (PMID 38773972, 2024). "In addition, research proves the significant role of SIRT4 in modulating mitochondrial glutamine metabolism and proliferation in Myc-driven tumor models of breast cancer." (PMID 38773972, 2024). "The differences in the expression patterns of SIRT4 in breast cancer cells may be attributed to differences in the breast cancer cell types and quantitation methods for SIRT4 used in these studies." (PMID 36291902, 2022). "In breast cancer, the expression pattern of SIRT4 is controversial." (PMID 36291902, 2022). "SIRT4, able to inhibit cancer stem cells proliferation and survival, is found downregulated in breast cancer, and its levels are inversely correlated to SIRT1 expression and linked to acquisition of breast cancer aggressive phenotype." (PMID 35328633, 2022). "Together, these results suggest that SIRT4 plays a key role in mammary tumor development, which might implicate MSC formation." (PMID 32863939, 2020). "Collectively, these data suggest that EX-527 might be an option for breast cancer patients with low SIRT4 expression." (PMID 32863939, 2020). "We proved for the first time that SIRT4 enhances sensitivity of breast cancer cells to tamoxifen." (PMID 31573734, 2019). "In addition, the level of p‐STAT3 Y705 in breast cancer cells with SIRT4 transfection and IL‐6 treatment was higher than that in cells with SIRT4 transfection only." (PMID 31573734, 2019). "Since SIRT4 and tamoxifen synergistically inhibited breast cancer cell proliferation, we next evaluated whether SIRT4 also promotes tamoxifen‐induced apoptosis." (PMID 31573734, 2019). "We next sought to determine whether STAT3 could reverse the effects of SIRT4 on the response of breast cancer cells to tamoxifen." (PMID 31573734, 2019). "To evaluate whether the inhibitory effect of tamoxifen on proliferation was influenced by SIRT4, we compared the relative viability of breast cancer cells under a tamoxifen concentration approximately equal to the IC50." (PMID 31573734, 2019). "SIRT4 acts as a tumor suppressor in liver cancer, breast cancer and colorectal cancer." (PMID 31817470, 2019). "Accordingly, our findings suggest that SIRT4 plays an important role in the sensitivity of ER‐positive breast cancer to tamoxifen and should be further studied to address the issue of drug resistance to endocrine therapies for breast cancer." (PMID 31573734, 2019). "Therefore, immunofluorescence was used to detect the localization of STAT3 in breast cancer cells after SIRT4 overexpression or depletion." (PMID 31573734, 2019). "As a mechanism, the authors revealed that SIRT4 deacetylation of MTHFD2 destabilizes MTHFD2 and causes its proteasomal degradation, leading to NADPH reduction and intracellular ROS accumulation in the breast tumors which, in turn, inhibits the proliferation of the breast cancer cells." (PMID 36291902, 2022). "Besides, we identified H4K16ac and BRCA1 as new prime targets of SIRT4 in breast cancer." (PMID 32863939, 2020). "However, critical mechanisms linking reduced SIRT4 expression to breast cancer progression remain unclear." (PMID 32863939, 2020). "Thus, SIRT4 enhances the sensitivity of breast cancer cells to tamoxifen." (PMID 31573734, 2019). "Normal breast epithelial cells MCF10A and breast cancer cell lines MCF-7, MDA-MB-231, BT549, MDA-MB-468 were used to establish SIRT4 gene knockdown and corresponding overexpression cells." (PMID 32863939, 2020). "SIRT4 targets H4K16ac and BRCA1 as new key factors in breast cancer cells and breast CSCs." (PMID 38397988, 2024). "Also, SIRT4 senses folate availability and controls MTHFD2 protein stability through regulating K50 acetylation, leading to the suppression of breast cancer cell proliferation." (PMID 37507016, 2023).
breast cancer (continued). "The SIRT4 protein was noticeably increased in the breast cancer cells compared with adjacent non-tumor cells and, via multivariate analysis, SIRT4 represents an independent predictive factor of good prognosis for breast cancer patients." (PMID 36230534, 2022). "Unlike in other human cancers, including breast cancer, the expression pattern of SIRT4 and its mechanistic roles in prostate cancer have been sparsely investigated." (PMID 36291902, 2022). "Sirtuin 4 (SIRT4) inhibits the expression of sirtuin 1 (SIRT1) by inhibiting glutamine metabolism, and SIRT1 promotes the deacetylation of H4K16 to regulate the stemness of breast cancer cells." (PMID 35004688, 2021). "To examine whether SIRT4 exerts similar functions in breast cancer, we conducted LC-MS/MS analysis of metabolites in mammary epithelial cells from SIRT4WT and SIRT4-/- mice (n = 6)." (PMID 32863939, 2020). "In conclusion, our data revealed that paeoniflorin promotes SIRT4 expression to enhance the sensitivity of ER-positive breast cancer cells to tamoxifen by suppressing STAT3 activation, suggesting that paeoniflorin could be used as a drug candidate for the treatment of ER + breast cancer." (PMID 35154350, 2022). "Additionally, a recent study demonstrated that SIRT4 deacetylates methylenetetrahydrofolate dehydrogenase/methylenetetrahydrofolate cyclohydrolase 2 (MTHFD2), a vital bifunctional enzyme in folate metabolism, to remodel folate metabolism against breast cancer cells." (PMID 36291902, 2022). "Importantly, SIRT4 inhibits the phosphorylation and nuclear translocation of STAT3, thereby inhibiting the STAT3 signaling pathway, and amplification of the target genes MYC and CCND1 of the STAT3 signaling pathway provide tamoxifen resistance in ER-positive breast-cancer cells." (PMID 33585187, 2020). "Without cell specificity, SIRT4 expression showed a time‐dependent increase and a significant decrease in GDH activity when breast cancer cells were cultured under low glucose conditions." (PMID 40625712, 2023).